MUC16 (mucin 16, cell surface associated)
Diseases named in the same sentence as MUC16 in open-access papers (continued):
Sharing a sentence is not in itself a finding about the gene and the disease.
ovarian tumor (continued). "While the shed MUC16 appears to have major influence on the cytolytic function of natural killer cells, the cell surface bound MUC16 is important for binding of the ovarian tumor cells to the mesothelial cells that line the peritoneal cavity." (PMID 19538730, 2009). "Extensive studies using human as well as murine ovarian tumor cell models are required to clearly define the function of MUC16 in the progression of ovarian tumors." (PMID 19538730, 2009). "The much higher expression of mucins (MUC1, MUC4, MUC5AC, MUC13 and MUC16) in ovarian tumors compared to the surrounding normal tissues can be exploited for the purpose of radioimmunodiagnosis (RID) and radioimmunotherapy (RIT)." (PMID 20034397, 2009). "Various studies have shown the overexpression of MUC1, MUC2, MUC3, MUC4, MUC5AC and MUC16 in a variety of ovarian tumors." (PMID 20034397, 2009). "In this study we demonstrate that Muc16 is expressed by murine ovarian tumor cells and can be detected by newly developed murine monoclonal antibodies that were initially generated against human MUC16." (PMID 19538730, 2009). "The ovarian tumor marker CA125 is expressed on human MUC16, a cell surface bound mucin that is also shed by proteolytic cleavage." (PMID 19538730, 2009). "The shed and cell surface bound MUC16 play important roles in the progression of human ovarian tumors." (PMID 19538730, 2009). "MUC16 facilitates the binding of ovarian tumor cells to mesothelial cells lining the peritoneal cavity." (PMID 19538730, 2009). "The mucin MUC16 and the glycosylphosphatidylinositol anchored glycoprotein mesothelin likely facilitate the peritoneal metastasis of ovarian tumors." (PMID 17067392, 2006). "Considering the potential importance of the mesothelin-MUC16 interaction in ovarian tumor metastasis within the peritoneum, we have performed additional studies to carefully define its molecular characteristics." (PMID 17067392, 2006). "The lower affinity of mesothelin for soluble MUC16 also makes it less likely that the mucin can act as a cross-linking agent by attaching to mesothelin expressed on the mesothelial and the ovarian tumor cells." (PMID 17067392, 2006). "In this study we utilize recombinant-Fc tagged human mesothelin to measure the binding kinetics of this glycoprotein to MUC16 expressed on the ovarian tumor cell line OVCAR-3." (PMID 17067392, 2006). "A recombinant fragment of MUC16 composed of the cytoplasmic region and a partial tandem repeat domain binds to mesothelin, a glycoprotein that is highly expressed by ovarian tumors and mesotheliomas." (PMID 17067392, 2006). "We also demonstrate that MUC16 positive ovarian tumor cells exhibit increased adherence to A431 cells transfected with mesothelin (A431-Meso+)." (PMID 17067392, 2006). "This wide range of mRNA transcript size, which may derive from differences in sample preparation, has contributed to the confusion over the molecular nature of MUC16 as expressed by different tissue types, including ovarian tumors." (PMID 38197671, 2024). "These shorter sequences may result from alternative splicing, but more patient samples will need to be sequenced to support or refute the hypothesis that alternative splicing of MUC16 occurs in ovarian tumors." (PMID 38197671, 2024). "Several examples involving the detection of alpha fetoprotein hepatocellular cancer biomarker and the CA125/MUC16 ovarian tumor circulating biomarker have employed SERS, SPR and SPRi applications without exploiting any other antifouling strategy besides the dilution of serum samples." (PMID 32531908, 2020). "CA125/MUC16 has been shown to inhibit cytolytic responses of human natural killer cells in ovarian cancer, therefore acting as a suppressor of the immune response directed against the ovarian tumors." (PMID 30134520, 2018).
ovarian tumor (continued). "If true, this model suggests that significant effect on ovarian tumors may be achieved by the application of small molecule agents and other strategies for in vivo knockdown of MUC16 or inhibition of its biological function." (PMID 24886523, 2014). "Finally, we consider previous and on-going efforts to develop therapeutic approaches to eradicate ovarian tumors by targeting MUC16." (PMID 24886523, 2014). "Immune editing in favor of cancer cells expressing higher levels of MUC16 may also increase peritoneal metastasis of ovarian tumors." (PMID 24886523, 2014). "Here, we show that MUC16, a heavily glycosylated 3-5 million Da mucin expressed on the surface of ovarian tumor cells, inhibits the formation of immune synapses between NK cells and ovarian tumor targets." (PMID 20089172, 2010). "Ovarian tumors present MUC16 as a Type I membrane glycoprotein on their cell surface." (PMID 20089172, 2010). "Cell binding studies suggested that mesothelin-MUC16 interaction could facilitate peritoneal metastasis of ovarian tumors." (PMID 17067392, 2006). "Mesothelin, like MUC16, is overexpressed by the ovarian tumor cells." (PMID 17067392, 2006). "Understanding the importance of MUC16-mesothelin binding may lead to novel therapies to control the peritoneal spread of ovarian tumors." (PMID 17067392, 2006). "The strong binding kinetics of the mesothelin-MUC16 interaction and the cell adhesion between ovarian tumor cells and A431-Meso+ even in the presence of peritoneal fluid strongly support the importance of these two glycoproteins in the peritoneal metastasis of ovarian tumors." (PMID 17067392, 2006). "Since the soluble MUC16 may inhibit mesothelin-MUC16 binding, the proposal that this interaction facilitates peritoneal metastasis of ovarian tumors seems counter-intuitive." (PMID 17067392, 2006). "This hypothesis is also supported by the observation that both mesothelin and MUC16 are co-localized in immunohistochemical studies of ovarian tumors." (PMID 17067392, 2006). "Here, we conduct Nanopore long-read sequencing of MUC16 transcripts from three primary ovarian tumors and established cell lines (OVCAR3, OVCAR5, and Kuramochi) for a more exhaustive and accurate estimation and sequencing of the MUC16 tandem repeats." (PMID 38197671, 2024). "Immunohistochemical analyses on different grades of ovarian tumor tissues indicated differential reactivity of CA125 and MUC16 CT mAbs." (PMID 29708979, 2018). "MUC16 binds to mesothelin, a GPI-anchored glycoprotein found on the surface of mesothelial cells and also overexpressed by ovarian tumors, with an apparent Kd of 5 nM." (PMID 24886523, 2014). "Different studies on the expression of mucins in ovarian tumors have shown overexpression of MUC1, MUC2, MUC3, MUC4, MUC5AC and MUC16 or CA125." (PMID 20034397, 2009). "The major objective of this study was to determine if the murine ovarian tumor cells, MOVCAR, express Muc16 and to characterize antibodies that recognize this mucin." (PMID 19538730, 2009). "Our recent and some previous studies showed the overexpression of MUC4 in a majority of early stage ovarian tumors and a combined panel of MUC1, MUC4 and MUC16 dramatically increased the sensitivity of MUC16 staining test." (PMID 20034397, 2009). "The major finding in this study is that MUC16 from six sources (three cancer cell lines and three ovarian tumors) contains 19 tandem repeats, rather than 63 as was previously reported." (PMID 38197671, 2024).
endometriosis (30 papers, 2013 to 2026). The growth of functional endometrial tissue in anatomic sites outside the uterine body. "There were several genes strongly expressed in endometriosis tissue: EPCAM, KRT18, WT1, MUC16, MUC1, and ESR1, if compared to the endometrial cells from healthy controls." (PMID 31717910, 2019). "MUC16’s specificity is hampered by its elevation in various non-cancerous conditions, such as endometriosis, cirrhosis, menstruation, pregnancy, pelvic inflammation, and uterine leiomyomata." (PMID 40836974, 2024). "However, observations of other conditions including nongynecological cancers and benign conditions such as endometriosis, as well as individuals during menstruation and pregnancy, reported elevated MUC16 serum concentrations." (PMID 26509158, 2015).
melanoma (30 papers, 2014 to 2025). A malignant, usually aggressive tumor composed of atypical, neoplastic melanocytes. "TTN mutations are a potential marker of poor prognosis in melanoma, which is amplified in the presence of concurrent MUC16 mutations." (PMID 39240165, 2024). "In non-small cell lung cancer (NSCLC) and melanoma cohorts, patients with MUC16 variants display superior outcomes with immune checkpoint inhibitor (ICI) therapy compared to wild-type patients." (PMID 38758220, 2024). "Overexpression of MUC16 is associated with poor prognosis in several malignant tumors, and mutations are associated with melanoma, etc.." (PMID 38792899, 2024). "In the realms of non-small cell lung cancer (NSCLC) and melanoma, the MUC16 gene mutation demonstrates a significant correlation with tumor mutation burden (TMB) and neoantigen load." (PMID 38758220, 2024). "TTN and MUC16 mutations were the most frequently mutated genes within this melanoma patient cohort and were the most common combination of concurrently mutated genes overall." (PMID 39240165, 2024). "Further genomic data analysis indicated that MUC16 mutations are prevalent in melanoma patients, with such variations closely linked to increased TMB and improved prognosis, potentially by activating immune pathways and enhancing T cell memory functions." (PMID 38361923, 2024). "Additional studies confirmed that mutations in MUC16 in melanoma are closely associated with higher TMB, increased overall survival, and positive responses to anti-CTLA-4 and anti-PD-1 therapies." (PMID 38361923, 2024). "MUC16 mutations have been reported to be involved in the increased expression level of immune checkpoint in melanoma patients." (PMID 38155221, 2023). "In melanoma, MUC16 alterations have been frequently found to be associated with BRAF V600E mutations and higher TMB than wild-type patients." (PMID 35884534, 2022). "The study also showed that MUC16-mutated melanoma patients treated with ICIs had significantly longer OS." (PMID 35312867, 2022). "Significant OS improvement was also observed in patients with melanoma with MUC16 mutation (median, 27.03 vs 9.73 months; hazard ratio, 0.57; 95% CI, 0.36-0.90; P = .02, log-rank test)." (PMID 32845327, 2020). "From the TCGA melanoma cohort, we found that patients with MUC16 mutation had the most significant association with high TML." (PMID 32491995, 2020). "At the same time, the mutation rate of TTN and MUC16 will increase in patients with CDKN2A deletion, which suggests that the increased mutation of TTN and MUC16 in this study may lead to metastasis of melanoma." (PMID 36891324, 2023). "Importantly, in melanoma, MUC16 is one of the critical mutated genes and is expected to be an alternative biomarker of tumor mutation burden." (PMID 36085074, 2022). "have previously proven that MUC16 mutations are mainly enriched in immune-associated pathways and are favorably linked with T-cell activation, which may enhance the prognosis of melanoma patients." (PMID 36532053, 2022). "We next confirmed the association between MUC16 mutation and OS in the melanoma cohort." (PMID 32845327, 2020). "All these findings suggested patients with MUC16 mutations may be more responsive to immunotherapies in melanoma and other relevant tumors." (PMID 32491995, 2020). "Noticeably, besides melanoma, our study showed other cancers benefited from immunotherapy (e.g., cancers of lung, colorectal, kidney, bladder, and head and neck) also exhibited the consistent association of MUC16 mutation with high TML." (PMID 32491995, 2020). "MUC16 was one of the most frequently mutated genes in melanoma." (PMID 32491995, 2020). "Among the melanoma patients, the most frequently mutated genes were TTN, MUC16, BRAF, DNAH5, and PCLO." (PMID 40781483, 2025). "Mutation profiling revealed frequent alterations in TTN (72%), MUC16 (67%), BRAF (51%), and other melanoma-associated genes." (PMID 41150769, 2025).
melanoma (continued). "We performed mutation analysis on melanoma samples, identifying TTN, MUC16, and BRAF as the most frequently mutated genes among the top 30 somatic mutations." (PMID 40639089, 2025). "Our study showed that MUC16 and TTN were the most common co‐occurrent mutations in this cohort of melanoma patients." (PMID 39240165, 2024). "We found that melanoma patients with TTN mutations alone and melanoma patients with both MUC16 and TTN mutations had worse prognosis than patients with neither MUC16 or TTN mutations." (PMID 39240165, 2024). "It is of note that in these three cases AHNAK2, MUC4, MUC16, and MUC17 mutations were found, which were previously reported to be involved in antitumoral immune mechanisms of melanoma." (PMID 36980598, 2023). "First, the mutation frequency of MUC16 in ACC (14%) was much lower than that in other solid tumors, such as GC (38.4%), lung adenocarcinoma (42.76%) and melanoma (73.86%)." (PMID 35568842, 2022). "The top 10 mutated genes in melanoma were TTN (72%), MUC16 (67%), DNAH5 (49%), PCLO (44%), LRP1B (38%), ANK3 (32%), DNAH7 (32%), ADGRV1 (35%), RP1 (33%), and BRAF (51%)." (PMID 33758620, 2021). "Results revealed that the presence of MUC16 mutations was significantly associated with high ICI response rate and overall survival in male patients from an ICI treated melanoma cohort." (PMID 32491995, 2020). "MUC16 mutation was associated with greater response rates in the NSCLC cohort (odds ratio, 4.03; 95% CI, 1.06-16.43; P = .03) and the melanoma cohort (odds ratio, 3.38; 95% CI, 1.07-14.25; P = .03)." (PMID 32845327, 2020). "Of the 183 melanoma patients in the ICGC cohort, the significantly high TML was also observed in patients with MUC16 mutations (median TML: 4.63 vs. 1.01; Wilcoxon rank sum test, P < 0.001)." (PMID 32491995, 2020). "The top 10 mutated genes in 467 melanoma patients are TTN (72%), MUC16 (67%), BRAF (51%), DNAH5 (49%), PCLO (44%), LRP1B (38%), ADGRV1 (35%), RP1 (33%), ANK3 (32%), DNAH7 (32%)." (PMID 33072607, 2020). "MUC16 mutation was associated with improved overall survival in both the NSCLC (hazard ratio, 0.34; 95% CI, 0.12-0.99; P = .04) and melanoma (hazard ratio, 0.57; 95% CI, 0.36-0.90; P = .02) cohorts." (PMID 32845327, 2020). "Mutations in the MUC16 and TTN genes commonly occur concurrently in these melanoma patients, but their combined prognostic significance stratified by gender and cancer subtype remains unclear." (PMID 39240165, 2024). "Therefore, we investigated the impact the two most commonly co‐occurrent genetic mutations, MUC16 and TTN, on patient prognosis and the impact of gender and melanoma subtype on patient mortality risk." (PMID 39240165, 2024). "Compared with BRAF, we suggest that MUC16 may be a more suitable biomarker for detecting the transformation of GCMN to melanoma in the Chinese population." (PMID 36085074, 2022). "Furthermore, the mutation of MUC16 was linked to better overall survival in both NSCLC and melanoma." (PMID 36532053, 2022). "We further examined the association of MUC16 mutation with outcomes in 2 ICI-treated cohorts, comprising 1 NSCLC cohort with 56 patients (median [IQR] age, 61 years; 24 men [43%]) and 1 melanoma cohort with 145 patients (median [IQR] age, 61 years; 98 men [67.6%])." (PMID 32845327, 2020). "In the TCGA cohort, melanoma patients with MUC16 mutations had a significantly higher TML than those without MUC16 mutations (median TML: 4.19 vs. 1.25; Wilcoxon rank sum test, P < 0.001)." (PMID 32491995, 2020). "In this study, we explored whether the presence of MUC16 mutations was associated with TML, tumor-immune microenvironment, survival outcome, and ICI treatment efficacy in melanoma." (PMID 32491995, 2020). "MUC16 mutation was associated with improved OS and response rates in anti-PD-1/PD-L1–treated patients with NSCLC, and this finding was verified in the independent melanoma cohort treated with anti-CTLA-4." (PMID 32845327, 2020).
melanoma (continued). "Therefore, our findings suggest that, although MUC16 and TTN mutations often occur concurrently, TTN mutations may be the primary driver of poor prognosis in melanoma patients." (PMID 39240165, 2024). "Mutation frequency analysis also revealed recurrent abnormalities in genes such as TTN, MUC16, and BRAF, which correspond to their recognized functions in melanoma development." (PMID 41150769, 2025). "In melanoma-related research, MUC1 and MUC16 have demonstrated distinct roles in tumor progression and immune responses." (PMID 38361923, 2024).
endometrial cancer (29 papers, 2015 to 2025). Primary or metastatic malignant neoplasm involving the endometrium (mucous membrane that lines the endometrial cavity). "MUC16 mutations can enhance the infiltration of cytotoxic T lymphocytes to enhance antitumor immunity in patients with endometrial cancer." (PMID 36176287, 2022). "In addition, somatic mutations have also been reported to be significantly associated with the prognosis of endometrial cancer such as MUC16 mutations and POLE exonuclease domain mutations." (PMID 31864301, 2019). "PERTINENT FINDINGS: HER2 and CD24 are abundantly expressed in endometrial cancer cells as well as patient-derived tissue samples representing several molecular subtypes of the disease, while the expression of MUC16 is more sparing and variable." (PMID 40841152, 2025). "We report on the evaluation of 3 antigens—human epidermal growth factor receptor 2 (HER2), mucin-16 (MUC16), and CD24—as potential radiotheranostic targets in endometrial cancer." (PMID 40841152, 2025). "Herein, we describe the exploration of 3 biomarkers—human epidermal growth factor receptor 2 (HER2), mucin-16 (MUC16), and CD24—as potential radiotheranostic targets for endometrial cancer." (PMID 40841152, 2025). "For the dataset of all mutations, the cancer type-specific six gene mutation biomarkers were APC for colorectal cancer, PTEN for endometrial cancer, BRAF for thyroid cancer and MUC16, DNAH5, TTN for cutaneous melanoma." (PMID 30662873, 2018). "QUESTION: Are HER2, MUC16, and CD24 promising radiotheranostic targets in endometrial cancer?" (PMID 40841152, 2025). "The atlas also contains diseased cells, including potential primary endometrial tumor cells in the uterus (MUC16+ non-ciliated uterus epithelial cells) and lung metastatic cells of endometrial cancer origin, as assessed by tumor gene signatures and histology (see accompanying manuscripts)." (PMID 38467625, 2024).